KCNQ1OT1 (KCNQ1 opposite strand/antisense transcript 1)
Diseases named in the same sentence as KCNQ1OT1 in open-access papers (continued):
Sharing a sentence is not in itself a finding about the gene and the disease.
cancer (continued). "KCNQ1OT1 is frequently recognized as being overexpressed in patients suffering from different cancers, including breast, bladder, and tongue." (PMID 35246252, 2022). "Treatment with LPS (6 μg/μL) reduced the transcript levels of CK2α and KCNQ1OT1 in human cancer cells." (PMID 35163809, 2022). "Overall, this study found that KCNQ1OT1 was transferred by cancer cell-derived exosomes to regulate PD-L1 ubiquitination through the miR-30a-5p/USP22 axis to enhance CRC immune escape." (PMID 36591473, 2022). "KCNQ1OT1 can affect the invasion of cancer cells by regulating the EMT process related to cell invaders." (PMID 35432529, 2022). "Collectively, these results indicate that KCNQ1OT1 acts as an anti-aging reagent and antioxidant in human cancer cells and lung fibroblasts." (PMID 35163809, 2022). "Since KCNQ1OT1 is secreted from cancer cells via exosomes, the reciprocal transfer of KCNQ1OT1 between cancer cells can substantially increase PD-L1 levels, contributing to immune evasion." (PMID 35055115, 2022). "LncRNA KCNQ1OT1, has also been evidenced to be related to the advance of multiple diseases, including cancer and cataract." (PMID 35170373, 2022). "KCNQ1OT1 knockdown promoted a senescence phenotype via downregulating CK2α in human cancer MCF-7 and HCT116 cells, and lung fibroblast IMR-90 cells." (PMID 35163809, 2022). "KCNQ1OT1 overexpression promoted the malignant behavior of cancer cells due to the autocrine effect of cancer cell-derived exosomes." (PMID 36591473, 2022). "Altogether, these results indicate that CR downregulated miR-760 by upregulating KCNQ1OT1, resulting in CK2α upregulation in human cancer cells." (PMID 35163809, 2022). "The purpose of this study was to explore the prognostic value and potential functional role of lncRNA KCNQ1OT1 across cancers." (PMID 33994860, 2021). "High expression of lncRNA KCNQ1OT1 was significantly related to poor survival in patients with CRC in a pan-cancer meta-analysis." (PMID 34630508, 2021). "It has been reported that knockdown of KCNQ1OT1 in cancer cell lines strongly inhibited cell migration and proliferation." (PMID 33345272, 2021). "KCNQ1 Opposite Strand/Antisense Transcript 1 (KCNQ1OT1) encodes a lncRNA from the opposite strand of KCNQ1 in the CDKN1C/KCNQ1OT1 cluster that is reported to play a vital role in the development and progression of cancer." (PMID 34827600, 2021). "lncRNA KCNQ1 opposite strand/antisense transcript 1 (KCNQ1OT1) was identified as an oncogene in human cancers." (PMID 34008749, 2021). "KCNQ1OT1 has been proved to play a key role in the migration, invasion, metastasis and recurrence of cancers." (PMID 34704918, 2021). "KCNQ1OT1 regulates cancer cell proliferation, cell cycle, migration and invasion, metastasis, glucose metabolism, and immune evasion." (PMID 34827600, 2021). "LncRNA KCNQ1OT1 is also packaged into exosomes and secreted by CAFs, thus inducing cancer cell proliferation, promoting the G1/S transformation of cancer cells, and increasing radiotherapy resistance." (PMID 35087824, 2021). "KCNQ1OT1 knockdown inhibited cancer hallmarks, including cell proliferation, metastasis, and radioresistance." (PMID 34827600, 2021). "The results showed that a high expression level of lncRNA KCNQ1OT1 in cancer tissue correlated with poor OS in patients with overall tumors (pooled HR=1.80, 95% CI: 1.17-2.78; P=0.008) with a random-effects model (I2=80%, P<0.001)." (PMID 33994860, 2021). "In this review, we focus on LncRNA KCNQ1OT1 and its molecular and biological functions in human cancer." (PMID 34827600, 2021). "We will thoroughly discuss the molecular and mechanistic role of KCNQ1OT1 in modulating oncogenic and biological functions, regulating cancer cell signaling mechanisms, and describe how its expression correlates to clinical features." (PMID 34827600, 2021). "We curated data from the LncTarD dataset to summarize the potential mechanism and function of lncRNA KCNQ1OT1 in various cancers." (PMID 33994860, 2021).
cancer (continued). "In the present review, we will explore current knowledge on the role of KCNQ1OT1 in the development of various human cancers." (PMID 34827600, 2021). "Next, we investigated the relationship between lncRNA KCNQ1OT1 and the survival of different cancer patients in the GEPIA database." (PMID 33994860, 2021). "Recent studies have shown that KCNQ1OT1 dysregulation participates in carcinogenesis and progression of human cancers." (PMID 31915311, 2020). "LncRNA KCNQ1OT1 has been reported to play roles in the pathogenesis of various cancer, such as colorectal cancer, breast cancer and tongue cancer." (PMID 32377169, 2020). "The axis of KCNQ1OT1/miR-16/PD-L1 in regulation of immune evasion and malignant behaviors of other cancers will be worthy of our attention." (PMID 32821247, 2020). "There is increasing evidence that kcnq1ot1 acts as a ceRNA to participate in the occurrence and development of malignant tumors and diabetic cardiomyopathy." (PMID 33293505, 2020). "Cumulative evidence suggests that KCNQ1OT1 promotes oncogenic phenotypes and chemoresistance of multiple cancers, including colon cancer, lung cancer, breast cancer, hepatocellular carcinoma, and tongue cancer." (PMID 32821247, 2020). "In the future, the search for a deep and reasonable mechanism for the role of KCNQ1OT1 will help us to understand its function more comprehensively and finally find a new method for the treatment of human malignant tumor." (PMID 32953888, 2020). "The results show that KCNQ1OT1 levels are significantly downregulated in cancer tissues (“Can”), as compared to its levels in the surrounding epithelial (“Epi”) tissues." (PMID 31915311, 2020). "Considering the necessity to overcome transporter-mediated resistance in cancer therapy, we investigated the role of KCNQ1OT1 in AED resistance in vitro and explored the potential mechanism." (PMID 31920517, 2019). "Additionally, the level of KCNQ1OT1 mRNA was reduced in LPS-induced senescent cells, and ectopic expression of KCNQ1OT1 suppressed LPS-mediated SASP factor expression in these cancer cells." (PMID 35163809, 2022). "Additionally, anti-cancer treatments such as As2O3 can result in decreased expression of KCNQ1OT1 in cardiac tissue." (PMID 35246252, 2022). "Only when KCNQ1OT1 was inhibited, this cancer-promoting effect was reversed (p < 0.05)." (PMID 34350172, 2021). "Overall, these results suggest that KCNQ1OT1 may play a role in developing OC and could be utilized as a biomarker to detect this cancer at earlier stages." (PMID 34827600, 2021). "The role of KCNQ1OT1 in various cancers was studied extensively." (PMID 33526991, 2021). "The subgroup results indicated that high expression of lncRNA KCNQ1OT1 was significantly correlated with poor OS in other types of cancer (pooled HR=1.92, 95% CI: 1.32-2.79, P<0.001) and CRC (pooled HR=2.19, 95% CI: 1.37-3.51, P=0.001) with low heterogeneity (I2=0, P>0.05)." (PMID 33994860, 2021). "In addition, IHC staining exhibited that the Ki67 (a marker of proliferation) was upregulated while GRP78 was down-regulated by KCNQ1OT1/XIST, suggesting that KCNQ1OT1/XIST promoted cancer cell proliferation but inhibited ERS activation." (PMID 34521445, 2021). "KCNQ1OT1, an oncogene, has been shown to promote the growth of cancer cells, including HCC." (PMID 34008749, 2021). "Accumulating evidences displayed that KCNQ1OT1 was a promising cancer-related lncRNA." (PMID 33345272, 2021). "Previous studies have suggested that lncRNA KCNQ1OT1 plays crucial roles in cancer biology." (PMID 31909901, 2020). "Although KCNQ1OT1 has been reported to act as a regulator of miRNAs in several cancers previously, this study describes a new downstream target miR-372-3p in KCNQ1OT1 regulation, which may be dependent on the variety of cell and tissue context." (PMID 33082306, 2020). "High KCNQ1OT1 expression was a predictor for poor overall survival of cancer patients." (PMID 31909901, 2020).
cancer (continued). "It is suggested that KCNQ1OT1 is an oncogene that promotes malignant progression of cancer cells." (PMID 32953888, 2020). "Recent studies exhibited that lncRNA KCNQ1OT1 was upregulated in various cancers." (PMID 32377169, 2020). "Considering the experience in cancer therapy, we aimed to investigate whether KCNQ1OT1 contributes to AED resistance via the ceRNA regulatory mechanism in PHT-resistant human brain microvascular endothelial cells in the present study." (PMID 31920517, 2019). "In addition, the role of the KCNQ1OT1/miR‐760/PPP1R1B axis should be investigated in other mechanisms of cancer cells resistance to chemotherapeutics." (PMID 30997746, 2019). "A recent study has indicated that lncRNA interactions with miRNA and mRNA—such as H19, MALAT1, and KCNQ1OT1, HULC, and HOTAIR—could be potential diagnostic and prognostic biomarkers in cancer." (PMID 31164794, 2019). "However, as yet little is known regarding the mechanism by which KCNQ1OT1 lncRNA is regulated and its functional role in cancer development." (PMID 26868975, 2016). "Thus, HULC, LINC02535, LINC00261, and KCNQ1OT1 may act as competing endogenous RNAs (ceRNAs) in various cancers, including HCC." (PMID 40699747, 2025). "Considering that KCNQ1OT1 promoted the progression and metastasis of various cancers, and was up-regulated in PC tissues, and negatively correlated with miR-15a level, we examined its regulation on miR-15a and the functional significance of KCNQ1OT1/miR-15a axis." (PMID 32821247, 2020). "Additional ncRNAs in this group have been studied in the context of cancer (e.g., THAP9-AS1, PURPL, OTUD6B-AS1), transcriptional regulation (e.g., KCNQ1OT1), and chromatin structure." (PMID 41369348, 2025). "Several lncRNAs involved in the local repression of imprinted loci also show significant deregulation in cancer, including KCNQ1OT1, H19, and maternally expressed gene 3 (MEG3), which are frequently overexpressed in a wide range of cancer types." (PMID 34668345, 2022). "Further, KCNQ1OT1 enhances the proliferation, migration, invasion, and EMT of cancer cells, while repressing their apoptosis." (PMID 33909822, 2021). "We also investigated commonly shared lncRNAs between COAD and READ (CRCs) and found the presence of MAGI2-AS3, GAS5, SNHG1, KCNQ1OT1, SNHG20, and MIR17HG in both cancers." (PMID 35140741, 2021). "In conclusion, overexpression of lncRNA KCNQ1OT1 is significantly related to malignant prognosis (OS) and clinicopathological features (TNM stage) in different types of cancers, especially CRC." (PMID 33994860, 2021). "All these studies about the roles of KCNQ1OT1, miR-148a-3p and ITGA5 in various cancers were in line with our present analysis." (PMID 33526991, 2021). "Moreover, KCNQ1OT1 was found could regulate the response of cancer cells to chemo‐reagents." (PMID 31909901, 2020). "Therefore, KCNQ1OT1 may be a new biomarker for cancer detection." (PMID 32953888, 2020). "However, KCNQ1OT1 and HES1 have higher expression in the carcinoma tissue compared with normal tissues." (PMID 36944972, 2023). "Of late, KCNQ1OT1 was observed to support ubiquitin-specific peptidase 22 (USP22)-mediated stabilization of PD-L1 by deactivating miR-30a-5p and thereby inhibiting the anti-cancer immunity of CD8+ T cells." (PMID 35055115, 2022). "Moreover, the relationship between the upregulation of KCNQ1OT1 and poor prognosis of CRC patients also suggested that higher KCNQ1OT1 levels in patients make them resistant to chemotherapy or other anti-cancer treatments." (PMID 34630508, 2021). "Similarly, the miR-329-3p/CTNND1 (Catenin delta-1) axis was demonstrated to interact with KCNQ1OT1 to modulate SW480 and LS1034 CRC cancer cell proliferation, migration, invasion, and apoptosis." (PMID 34827600, 2021). "Nevertheless, because of the limited sample size and discrete outcomes of previous independent studies, there is no consensus on the prognostic value of lncRNA KCNQ1OT1 in cancer patients." (PMID 33994860, 2021).
cancer (continued). "Hence, we will perform animal experiments in the near future to validate the KCNQ1OT1/MIR‐142‐5p/CAPN10 axis in OC and to confirm their roles in regulating cancer progression." (PMID 31909901, 2020). "Prediction of targets of lncRNA LOC441178 in silico using a lncRNA-RNA interactions database showed that LOC441178 will potentially interact with both coding and non-coding RNAs, some of which are related to cancer, such as coding mRNA MUC16/CA125, and non-coding RNA KCNQ1OT1." (PMID 28415559, 2017). "Hence, KCNQ1OT1 was suppressed in Huh7/SNU449 cells using CRISPR technology and observed regression of oncogenic properties with enhanced chemosensitivity and reduced metastasis in cancer cells." (PMID 38851743, 2024). "In the case of KCNQ1OT1, its role in locally silencing the expression of the neighboring tumor suppressor cyclin‐dependent kinase inhibitor 1C (CDKN1C) may account for its oncogenic deregulation in cancers." (PMID 34668345, 2022). "We obtained a six-gene signature (APOBEC3B, GOLM1, FAM117A, KCNQ1OT1, PCDHB2, and USP43) with the ability to predict overall survival and progression-free survival (PFS), which could translate into a prediction of the response to the cancer treatment received." (PMID 35565183, 2022). "Similarly, KCNQ1OT1 (Potassium voltage-gated channel subfamily Q member 1 opposite strand 1), one imprinted antisense lncRNA located in KCNQ1 loci on human chromosome 11p15.510, has been reported to play an oncogenic role in several human cancers." (PMID 33082306, 2020). "It should be considered, however, that the inconsistency of the methylation changes of the imprinted loci outside of 11p15.5 suggests that apart from H19/IGF2 and KCNQ1OT1/CDKN1C, the other imprinted genes do not likely act as drivers of cancer progression in WT." (PMID 33217932, 2020).
infection (4 papers, 2010 to 2023). The state of being infected such as from the introduction of a foreign agent such as serum, vaccine, antigenic substance or organism. "To confirm the functional role of KCNQ1OT in osteogenic differentiation upon SpA-infection, we overexpressed KCNQ1OT1 in SpA-treated hBMSCs (0.5 μg/ml) by transfecting the cells with the ad-KCNQ1OT1 vector." (PMID 35226820, 2022). "To further evaluate the effects of KCNQ1OT1 on TSCC cell tumorigenesis and chemo-resistance in vivo, we generated KCNQ1OT1 stable knockdown CAL27 cells by lentiviral infection." (PMID 29970910, 2018).
cardiovascular disease (3 papers, 2020 to 2022). "KCNQ1OT1 has been reported to be associated with numerous types of disease, including cardiovascular diseases." (PMID 34698362, 2021). "In addition, KCNQ1OT1 was shown to be an essential lncRNA involved in the regulation of a cardiovascular disease ceRNA network, and it could function as a molecular sponge by binding to miRNAs to regulate the expression of their downstream target genes." (PMID 34698362, 2021). "In addition, lncRNAs are also emerging as biomarkers for cardiovascular diseases; for example, ANRIL, KCNQ1OT1, and MIAT are markers of left ventricular dysfunction in postmyocardial infarction." (PMID 35392816, 2022).
colorectal (3 papers, 2020 to 2021). "In conclusion, our data shows that KCNQ1OT1 regulates colorectal carcinogenesis by upregualting aerobic glycolysis via HK2." (PMID 32564010, 2020). "In conclusion, our study demonstrates that high KCNQ1OT1 expression promotes colorectal carcinogenesis by enhancing aerobic glycolysis through direct binding and stabilization of hexokinase 2 (HK2)." (PMID 32564010, 2020). "KCNQ1OT1 and SNHG1 possessed hub nodes properties in all of the four context-specific ceRNA networks, implying significant potential in regulating colorectal carcinogenesis." (PMID 33194594, 2020).
neurological disorders (3 papers, 2017 to 2024). "For instance, KCNQ1OT1 inhibition can reduce neuronal apoptosis and neuroinflammation by controlling the miR-30e-3p/NLRP3 axis, indicating that KCNQ1OT1 and miR-30e-3p may be promising therapeutic targets for the treatment of neurological disorders." (PMID 39021183, 2024). "KCNQ1OT1, which is highly expressed in TBI mice, and its suppression could reduce neurological disorders, inflammation, and the suppression of cerebral oedema through microglia activity reduction." (PMID 35266286, 2022).
KCNQ1OT1 also shares sentences with these, for which no sentence is quoted: acute myocardial infarction (4 papers); Wilms tumour (3); autism (2); cardiomyopathy (2); coronary artery disease (2); embryonal tumours (2); Prader-Willi syndrome (2); acute lung injury (1); adrenal cortical tumors (1); adrenal tumors (1); Biotin deficiency (1); Carney complex (1); cervical tumors (1); chordoma (1); chronic hepatitis C (1); cognitive decline (1); congenital generalized lipodystrophy (1); cystic renal disease (1); dengue (1); diffuse large B-cell lymphoma (1); female infertility (1); Frasier syndrome (1); glioblastoma (1); growth deficiency (1); heart diseases (1); hepatitis C virus infection (1); hepatoblastoma (1); idiopathic pulmonary fibrosis (1); injury (1); insulinomas (1).
A further 32 diseases each share a sentence with KCNQ1OT1 in 1 paper.